MTOR (mechanistic target of rapamycin kinase)
Diseases named in the same sentence as MTOR in open-access papers (continued):
Sharing a sentence is not in itself a finding about the gene and the disease.
lung adenocarcinoma (continued). "Finally, BIM and mTOR expression were determined in our panel of EGFR-mutant lung adenocarcinoma cell lines and correlated with the half maximal inhibitory concentration (IC50) of gefitinib." (PMID 26639561, 2015). "Additionally, in lung adenocarcinoma cell lines, the expression of miR-143 was found to be repressed by mTOR and the mTOR signaling was inhibited by everolimus in our study." (PMID 23251295, 2013). "Metformin exerted antitumor activities in part by regulating the AFAP1-AS1/miR-3163/secreted phosphoprotein 1 (SPP1) axis in lung adenocarcinoma, and miR-316 overexpression caused suppression of PI3K/AKT/mTOR signaling, which could be re-activated by SPP1 overexpression." (PMID 37686205, 2023). "It has been reported that hsa-mir-193b-3p is closely related to lung adenocarcinoma, and its expression level is significantly elevated in lung adenocarcinoma tissues, and associated with signaling pathways such as PI3K-Akt signaling pathway, MAPK signaling pathway, and mTOR signaling pathway." (PMID 37335738, 2023). "Therefore, we speculated that the mPRα‐mediated regulation of adiponectin may also influence the proliferation of lung adenocarcinoma through the AMPK/mTOR signaling pathway." (PMID 32529777, 2020). "Moreover, microtubule-regulating kinesins, such as KIF18B, are involved in accelerating cell proliferation, migration, and invasion via mediating AKT/mTOR, and thereby contribute to advanced tumor stage and correlates with unfavorable prognosis in lung adenocarcinoma patients." (PMID 32631334, 2020). "Additionally, p-mTOR and p-eIF4E was dramatically higher in lung adenocarcinoma (both P<0.05)." (PMID 32023262, 2020). "PI3K/Akt/mTOR signaling plays a crucial role in regulating autophagy, therefore, an autophagy marker, namely microtubule-associated protein light chain B (LC3B) protein, was used to assess whether FIP-nha suppressed autophagy in lung adenocarcinoma cells." (PMID 30388826, 2018). "In an exploratory analysis, the protein and mRNA expression levels of DGKa, PDE4A and PDE4D were examined in the five EGFR-mutant lung adenocarcinoma cell lines in an effort to explore whether DGKa regulates MTOR transcription through modulation of cAMP levels." (PMID 26639561, 2015). "In conclusion, our study demonstrates that β-elemene effectively reverses cisplatin resistance in lung adenocarcinoma by downregulating the long non-coding RNA LINC00511, thereby suppressing the PI3K/AKT/mTOR signaling pathway." (PMID 41480385, 2025). "Succinylation and acetylation cooperatively regulate protein function and metabolism in lung adenocarcinoma, modulating significant signaling pathways such as ERBB and mTOR to promote tumor growth." (PMID 40865948, 2025). "Compared with those in the adjacent noncancerous tissue (ANCT) group, high expression of NR6A1 was observed in the lung adenocarcinoma (LUAD) group, whereas the protein levels of HK1 and p-mTOR were high in the LUAD group." (PMID 41219936, 2025). "We confirmed that high expression of NR6A1 in lung adenocarcinoma tissues was significantly positively correlated with HK1 and p-mTOR expression." (PMID 41219936, 2025). "It has been reported that dioscin, a therapeutic agent for lung adenocarcinoma, can suppress the proliferation, invasion and EMT of lung cells via the inactivation of AKT/mTOR/GSK3β signaling pathway." (PMID 40768543, 2025). "For example, in lung adenocarcinoma (LUAD), FBXO32 degrades the cancer suppressor gene PTEN through ubiquitination, removing its inhibition on the PI3K/AKT/mTOR pathway, resulting in abnormal activation of AKT/mTOR signaling." (PMID 40534867, 2025). "Moreover, Rapamycin, the mTOR inhibitor, is proved to effectively suppress Rab22a-triggered proliferation, migration and invasion in lung adenocarcinoma cells, indicating that Rab22a regulates the biological malignancies of lung adenocarcinoma cells through activating PI3K/AKT/mTOR signaling." (PMID 38695990, 2024).
lung adenocarcinoma (continued). "In summary, our study highlights the role of FBXO32 in promoting the PI3K/AKT/mTOR pathway via PTEN degradation, thereby fostering lung adenocarcinoma progression." (PMID 38643215, 2024). "As demonstrated in vitro in human lung adenocarcinoma cells, YAP regulates proliferation via the PTEN/AKT/mTOR signaling pathway; specifically, YAP inhibits PTEN and activates the AKT/mTOR pathway." (PMID 38802925, 2024). "Aberrant activation of EGFR downstream signaling pathways, mainly including PI3K/AKT/mTOR and MAPK/ERK, is a crucial trigger for the initiation of lung adenocarcinoma." (PMID 37239162, 2023). "Tomeka et al27 recently evaluated FBXO17 expression in lung adenocarcinoma cells, where it was observed that it accelerated the progression of the tumor by regulating the PI3K-Akt-mTOR pathway." (PMID 36035375, 2022). "PCNP can regulate the progression of human lung adenocarcinoma cells via the STAT3/5 and PI3K/Akt/mTOR signaling pathways." (PMID 36591491, 2022). "Together, these data suggest that AKT/mTOR and EMT pathway activation in invasive lung adenocarcinoma cells is dependent upon aurora kinase signaling." (PMID 35332150, 2022). "In conclusion, we demonstrate that Hippo pathway critical transcriptional coactivators YAP manipulates the proliferation of lung adenocarcinoma, which was regulated by PTEN/AKT/mTOR autophagic signaling." (PMID 33413409, 2021). "Curcumin inhibits the growth of malignant gliomas, lung adenocarcinoma and melanoma cells in vitro and in vivo by downregulating the PI3K/AKT/mTOR signaling pathway and activating the AMPK pathway, and finally by promoting autophagy." (PMID 34575981, 2021). "Hippo pathway critical transcriptional coactivators YAP manipulates the proliferation of lung adenocarcinoma, which is regulated by PTEN/AKT/mTOR autophagic signaling." (PMID 33413409, 2021). "PC4 also decreases lung adenocarcinoma cell sensitivity to the HIF-PH inhibitor DMOG and the mTOR inhibitor rapamycin." (PMID 34899911, 2021). "Many studies have reported that the PI3K–Akt signaling pathway, the Ras signaling pathway, the neurotrophic-signaling pathway, the mTOR-signaling pathway, and the MAPK signaling pathway are regulated in the development of lung adenocarcinoma patients." (PMID 33050659, 2020). "Furthermore, consistent with our previous study, it was observed that PLCγ1 inhibition blocked mTOR and ULK1 phosphorylation in lung adenocarcinoma A549 cells, suggesting thereby that the suppression of PLCγ1/mTOR/ULK1 axis might contribute to PLCγ1 inhibition-driven autophagy." (PMID 32210730, 2020). "Intriguingly, delivery of urocanic acid-modified chitosan-mediated PTEN gene aerosol into lung adenocarcinoma KRAS mutant in vivo models increased PTEN levels and downregulated the oncogenic mTOR/Akt axis." (PMID 31404976, 2019). "Liver kinase B1 (LKB1)/mammalian target of rapamycin (mTOR) signaling axis regulates ECM stiffness and participates in lung adenocarcinoma progression." (PMID 31552191, 2019). "Our study elucidates that PCNP can regulate the procession of human lung adenocarcinoma cells via STAT3/5 and PI3K/Akt/mTOR signaling pathways." (PMID 30872582, 2019). "Our previous data suggested that the AKT/mTOR signaling pathway is necessary for ROR1-mediated proliferation and antiapoptosis in lung adenocarcinoma." (PMID 31452776, 2019). "Inversely, the negatively regulated genes by mTOR signaling (gene set: MTOR_UP.N4.V1_DN, right) were enriched in the PGAM1-low expression groups, in both lung adenocarcinoma (ADC) and lung squamous cell carcinoma (SCC) subtypes of NSCLC." (PMID 29362480, 2018). "PD-L1 expression correlated with mTOR activation in human lung adenocarcinomas and squamous cell carcinomas, suggesting that oncogenic AKT-mTOR activation promotes immune escape through PD-L1 upregulation." (PMID 29662490, 2018).
lung adenocarcinoma (continued). "Taken together, our study demonstrated that miR-206 overexpression in human lung adenocarcinoma cisplatin resistant cells inhibited the EMT and cisplatin resistance by targeting MET and suppressing its downstream PI3K/AKT/mTOR signaling pathway." (PMID 27014910, 2016). "Ectopic expression of miR-206 mimics inhibited cisplatin resistance, decreased the migration and invasion in cisplatin-resistant lung adenocarcinoma cells, partly due to inactivation of MET/PI3K/AKT/mTOR signaling pathway." (PMID 27527856, 2016). "When we examined PI3K/AKT/mTOR signaling pathways to explain ROR1-mediated survival signals in lung adenocarcinomas, we found that silencing of ROR1 significantly decreased phosphorylation of both AKT and mTOR in ROR1+ PC-9 and NCI-H1975 cells." (PMID 25978653, 2015). "In EGFR-mutant lung adenocarcinoma cell lines with high BIM expression, concomitant high mTOR expression increased IC50 of gefitinib for cell proliferation." (PMID 26639561, 2015). "Relative to the other lung adenocarcinoma cell lines tested, IO33 cells were most resistant to inhibition of proliferation by rapamycin in vitro despite inhibition of mTOR." (PMID 19330036, 2009). "Similarly, in lung adenocarcinoma, HKDC1 promotes the tumorigenesis and bolsters glycolytic flux via the AMPK/mTOR signaling pathway, thereby facilitating invasiveness." (PMID 41049000, 2025). "In lung adenocarcinoma, HKDC1 may influence the AMPK/mTOR signaling pathway to enhance proliferation, migration, invasion, glycolysis, EMT, and tumorigenicity." (PMID 41049000, 2025). "The mechanism by which metformin inhibits lung adenocarcinoma cell proliferation may be related to glucose metabolism regulated by PI3K/AKT signalling and mTOR signalling pathways." (PMID 38811809, 2024). "Furthermore, the mammalian target of the rapamycin (mTOR) pathway upregulates GLUT3, and a link between oncogenic EGFR signaling and GLUT3 has also been demonstrated in lung adenocarcinoma." (PMID 37047055, 2023). "The gene set enrichment analysis showed that a higher expression of CPN2 may participate in mTOR, TGF-BETA, NOTCH, TOLL-like-receptor, WNT, and MAPK signaling pathway in lung adenocarcinoma." (PMID 35686102, 2022). "Supporting our findings, mRNA levels of NOP56 significantly correlate with that of mTOR pathway genes in KRAS-mutant cancer cells and lung adenocarcinomas, and NOP56 expression is a predictive marker of sensitivity to mTOR inhibitors in KRAS-mutant but not KRAS-wild-type cancer cells." (PMID 35039048, 2022). "Further analysis (Western blot) confirmed that FIP-nha induced a dose-dependent (0–16 μg/mL) decrease in the expression of both Akt (p-Akt) as well as mTOR (p-mTOR), thus confirming the critical role of PI3K/Akt pathway in A549 and H2347 lung adenocarcinoma cells." (PMID 34771120, 2021). "Furthermore, PC4 mediated lung adenocarcinoma cell sensitivity to the HIF-PH inhibitor DMOG and the mTOR inhibitor rapamycin, and PC4 mediated the synergistic effect of DMOG and cisplatin." (PMID 34899911, 2021). "Therefore, AMPKα, mTOR, and ERK signals were involved in PLCγ1 inhibition-driven autophagy in human lung adenocarcinoma A549 cells." (PMID 32210730, 2020). "In the presence of leptin, lung adenocarcinoma PTEN-null cells proliferated and migrated with a higher rate through the upregulation of the oncogenic pathways PI3K/mTOR/Akt, MAPK, JAK/STAT3, establishing a positive feedback among them that was abrogated after pathway targeted inhibition." (PMID 31404976, 2019). "In addition, our findings reveal that PCNP mediates the proliferation, migration, and invasion of human lung adenocarcinoma cells via STAT3/5 and PI3K/Akt/mTOR signaling pathways." (PMID 30872582, 2019). "In the current study, we demonstrated that miR-206 could suppress EMT process and cisplatin resistance of lung adenocarcinoma cells, partly through targeting MET and its downstream PI3K/AKT/ mTOR pathway both in vitro and in vivo." (PMID 27014910, 2016).
lung adenocarcinoma (continued). "HKDC1 demonstrates significant upregulation in lung adenocarcinoma, where it critically promotes oncogenic processes including cell proliferation, migration, invasion, epithelial-mesenchymal transition (EMT), and tumorigenicity while enhancing glycolysis through the AMPK/mTOR signaling pathway." (PMID 41049000, 2025). "Finally we show that SMARCA4 proficient lung adenocarcinoma have higher AKT and mTOR activation." (PMID 40069402, 2025). "We previously reported that the mTOR pathway not only serves as a predictive marker for sensitivity to the combination of the EGFR‐TKI inhibitor WZ4002 and trametinib, but also is involved in acquired resistance to this combination treatment in EGFR mutant lung adenocarcinoma." (PMID 32191822, 2021). "Furthermore, miR-145 inhibited cell proliferation and promoted cell apoptosis through negatively regulating mTOR signaling pathway and decreasing MMP-2 and MMP-9 expression, the Bax/Bcl-2 ratio and the activity of the caspase-3 cascade in human lung adenocarcinoma A549 cells." (PMID 31582906, 2019). "In a paper about TCGA lung adenocarcinoma published by TCGA Research Network, RPPA, which provides proteomic and phosphoproteomic phenotypic evidence of pathway activity, revealed significant activation of mTOR and its effectors in a substantial fraction of the tumors." (PMID 26556867, 2015). "In CD133+ lung adenocarcinoma stem cells, we found that gal-1 knockdown significantly reduced COX-2 expression and PGE2 secretion, and the phosphorylation levels of AKT and mTOR, more importantly, exogenous galectin-1 could partially rescue the influence of galectin-1 knockdown." (PMID 25605013, 2015). "Fourth, PRMT5 directly co-localized and interacted with AKT, albeit not with PTEN and mTOR; Akt phosphorylation at Thr308 and Ser473 and the downstream target GSK3 at Ser9 was markedly decreased without altering PTEN and mTOR phosphorylation at Ser2442 in PRMT5-deficient lung adenocarcinoma cells." (PMID 35493527, 2022). "This suggests that activation of the MAPK, PI3K/mTOR and IFNγ pathways is related to increased CD274 mRNA levels in lung adenocarcinomas without targetable genetic alterations." (PMID 30972766, 2019).
Sepsis (176 papers, 2009 to 2026). Sepsis is defined as life-threatening organ dysfunction caused by a dysregulated host response to infection. "to clarify the endoplasmic reticulum stress (ERS) status of CD4+ T lymphocytes in sepsis patients, particularly elderly individuals aged over 65 years, and to elucidate its association with mTOR-mediated autophagic-lysosomal disorder." (PMID 40933998, 2025). "In conclusion, PTX3 inhibits apoptosis caused by excessive autophagy by inhibiting the PI3K/AKT/mTOR signaling pathway, thereby alleviating the progression of sepsis." (PMID 38784395, 2024). "Zinc finger antisense 1 (ZFAS1), which is activated by the transcription factor SP1, can induce pyroptosis in cardiomyocytes by targeting the miR-590-3p/AMPK/mTOR signal, and aggravate cardiac dysfunction caused by sepsis." (PMID 37872948, 2023). "It was finally proved that IFNγ promoted the Warburg effect through the PI3K/Akt/mTOR pathway to reverse the immunosuppression caused by sepsis." (PMID 37434129, 2023). "In the later stage of sepsis, inadequate and maladaptive autophagy occurs, which is associated with upregulation of mammalian target of rapamycin (mTOR) signaling." (PMID 35706715, 2022). "This is the first time that mTOR proved to be involved in the CD4+ T cell apoptosis caused by ROS-mediated ERS in sepsis." (PMID 35915740, 2022). "Increased expression of KIM-1 (kidney injury molecule-1) and mTOR (mammalian target of rapamycin) was found in sepsis-associated AKI." (PMID 33467524, 2021). "In the skeletal muscle of mice with sepsis, decreased mTOR activation is associated with reduced protein synthesis." (PMID 30154452, 2018). "Similar results were obtained for the levels of the proinflammatory cytokines, TNF-α and IL-1β, indicating that SIRT3 knockout increased inflammatory responses associated with sepsis-induced AKI through the AMPK/mTOR/autophagy pathway." (PMID 30487750, 2018). "In the present study, we used rapamycin, an inhibitor of the mTOR pathway, to explore the role of the mTOR pathway and the relationship between autophagy and the mTOR pathway in cardiac dysfunction caused by sepsis." (PMID 30050390, 2018). "Our data confirm prior observations that in murine models of sepsis, decreased muscle protein synthesis is associated with a decrease in mTOR signaling as well as increased muscle protein degradation." (PMID 27811170, 2016). "This clinical study was designed to evaluate the intensity of ERS and its associated CD4+ T cell apoptosis in elderly sepsis patients, and explore the correlation between mTOR-mediated autophagic-lysosomal disorder and ERS, providing evidence for future preclinical and clinical research." (PMID 40933998, 2025). "In summary, we may have found a contribution of the mTOR-autophagy-CTLA4 axis in sepsis-associated CD4+ T cell deficiency and dysfunction." (PMID 39104632, 2024). "Indeed, previous studies have demonstrated that platelet-derived exosomes can enhance the production of neutrophil extracellular traps (NETs) in sepsis by activating the autophagy-associated AKT/mTOR signaling pathway." (PMID 38161332, 2023). "Additionally, the pathogenesis of sepsis is associated with mTOR signaling, NF-κB signaling pathway, calcium signaling, calcium transport, and tRNA charging pathway." (PMID 37752563, 2023). "The glycaemic response to sepsis is well-recognized and has been clearly linked to upregulation of glycolytic pathways in immune cells with involvement of cellular energy sensors such as mechanistic target of rapamycin (mTOR) and AMPK." (PMID 35911546, 2022). "We speculate that mTOR might also function as import regulator during the process of CD4+ T cell apoptosis caused by ERS in sepsis." (PMID 35915740, 2022). "Therefore, we designed the present study to investigate the molecular mechanisms underlying autophagic flux deficiency in CD4 + T cells during sepsis and to explore the roles of mTOR pathway in modulating CD4 + T cell survival." (PMID 35435531, 2022).